SMARCC1 (SWI/SNF related BAF chromatin remodeling complex subunit C1)
Diseases named in the same sentence as SMARCC1 in open-access papers (continued):
Sharing a sentence is not in itself a finding about the gene and the disease.
squamous cell carcinoma (1 paper, 2020). A carcinoma arising from squamous epithelial cells. "Next, n = 116 samples of patients with pure squamous cell carcinoma (n = 68) and mixed urothelial carcinoma with substantial squamous differentiation (n = 48) were analyzed for seven SWI/SNF complex proteins (ARID1A, SMARCA4, SMARCB1, SMARCC1, SMARCC2, SMARCA2 and PBRM1) by immunohistochemistry." (PMID 33227989, 2020).
cancer (39 papers, 2008 to 2025). A tumor composed of atypical neoplastic, often pleomorphic cells that invade other tissues. "The results showed that SMARCC1 expression was obviously associated with the expression of immune checkpoints on immune cells and cancer cells, including PD-1, PD-L1, PD-L2, and CTLA-4." (PMID 34937564, 2021). "At least 20% of all human cancers contain mutations in the SWI/SNF complex including Swi3 homolog BAF155/SMARCC1 and BAF170/SMARCC218,30,31." (PMID 32528012, 2020). "SWI/SNF-related, matrix-associated, actin-dependent regulator of chromatin subfamily C member 1 (SMARCC1) protein is a potential tumor suppressor in various cancers." (PMID 34249931, 2021). "Interestingly, with INI1 than that of the other two core subunits encoding the SWI/SNF complex (BAF155/SMARCC1 and BAF170/SMARCC2), which are rarely mutated in human cancers, suggesting that mutations in IN1 increase the risk of cancer in individuals." (PMID 36883311, 2023). "To date, SMARCC1 has been reported to be overexpressed in various cancers." (PMID 35669562, 2022). "Furthermore, upregulation of SMARCC1 has been identified in several solid human cancers, including prostate cancer and myxoid liposarcoma." (PMID 35669562, 2022). "For E2F3, SOX4, CBFB and SMARCC1, the transcript analyses were corroborated by an in-depth IHC analysis not only confirming their increased expression level, but also demonstrating their expression by the cancer cells." (PMID 19156145, 2009). "Our transcript analyses of CBFB and SMARCC1 did not reveal any association, not even a trend, to recurrence of stage II cancer." (PMID 19156145, 2009). "For the remaining 17 genes, DNMT3B, RARB, SMAD5, SMARCA5, SMARCC1 and TGFBRAP1 were predicted only by our method, but various evidence suggests that they have a driving role in cancer development." (PMID 39186807, 2024). "SMARCC1, as a SWI/SNF chromatin remodeling factor, has been reported to play important roles in many cancers." (PMID 34937564, 2021). "Therefore, SMARCC1 is pivotal as its modification by CARM1 directly impacts gene regulation and cancer progression." (PMID 39468330, 2024). "Among the SCGT-derived clones with GCsapM-ADA integration, SMARCC1 expression was also analyzed, although it has not been categorized as a cancer gene." (PMID 34786435, 2021). "SMARCC1 is a regulator of gene transcription through chromatin remodelling, and is found in exosomes in cancer with no reported function in the joint." (PMID 28611391, 2017). "Cell cycle, cancer and cell morphology are the top functions influenced by genes in Network A. Sixteen genes differentially expressed between NC and CIN III are involved in this network including RBL2/p130, SMARCC1, NCOR1, PTEN, DHFR and CDKN2B." (PMID 18248679, 2008). "However, SMARCC1 has not been reported as a cancer gene, and its expression level did not increase." (PMID 34786435, 2021). "Whether these vector integrations facilitate the proliferation of clones remains unclear because these genes in the dominant clones (LOC100130950 and TRAP1 in Pt1 and SMARCC1 in Pt2) were not categorized as cancer genes, or their expression levels did not increase." (PMID 34786435, 2021). "Following induction of DNA damage by Dox, SMARCC1 immunoprecipitation of the chromatin-bound fraction in cancer cells without ASS1 demonstrated decreased levels of SMARCC1 protein and lower levels of succinated SMARCC1." (PMID 38858597, 2024).
tumor (27 papers, 2009 to 2025). "Univariable analysis demonstrated that high SMARCC1 expression, T stage and tumor-node-metastasis (TNM) stage were potential risk factors for decreased OS in HCC." (PMID 34937564, 2021). "Through data mining and tissue microarray verification, we found that the protein and mRNA levels of SMARCC1 are high in tumor tissues, which has remarkable diagnostic value in HCC patients." (PMID 34937564, 2021). "SMARCC1 is a core member of the tumor suppressing SWI-SNF chromatin remodelling complex and also affected by succination." (PMID 35912170, 2022). "In ccRCC, SMARCC1 is commonly deleted because of its position on chromosome 3, which is known as a potentially tumor-promoting region in RCC." (PMID 35912170, 2022). "Then, we performed SMARCC1 knockdown and overexpression in HCC cell lines and confirmed the relevant tumor-promoting functions of SMARCC1 in vitro." (PMID 34937564, 2021). "The in vivo studies using a murine model showed that SMARCC1 knocking down led to the acceleration of tumor growth and lung metastasis." (PMID 34249931, 2021). "It is worth noting that in recent reports, the SWI/SNF chromatin remodelling complex, in line with our observations (SMARCC1), has become increasingly recognised for its role in tumour suppression." (PMID 19156145, 2009). "These consistent findings suggest that the expression of PBX2, PRMT1, SMARCC1, and IGF2BP2 in tumor tissues could serve as reliable diagnostic markers for HNSCC due to their high sensitivity and specificity." (PMID 40270464, 2025). "In addition, related studies have reported that ARID2, SMARCC1, SMARCD1‐3 and other subunits have a low mutation probability in tumours, which is manifested as delection." (PMID 36883311, 2023). "SMARCC1 knockdown cells exhibited significantly larger tumor volume and weight than control cells." (PMID 34249931, 2021). "Overall, we found that SMARCC1 affects immune infiltration and plays a tumor-promoting role in HCC." (PMID 34937564, 2021). "Taken together, SMARCC1 may function as a tumor suppressor in PCa along with other epigenetic factors, which warrant further investigation." (PMID 34249931, 2021). "Due to the tumor-promoting role of SMARCC1, treatments inhibiting DNA methyltransferases and transcription factors or weakening the role of SMARCC1 in immune infiltration might improve the survival of HCC patients." (PMID 34937564, 2021). "Finally, we identified a positive correlation between SMARCC1 and tumor-infiltrating immune cells." (PMID 34937564, 2021). "Clinical data analysis revealed a strong correlation between high levels of PBX2, PRMT1, SMARCC1, and IGF2BP2 with poor prognosis and tumor progression in HNSCC patients." (PMID 40270464, 2025). "Clinical NB cases with up‐regulation of KPNB1, CNBP, SMARCC1, SMARCA4 or down‐regulation of SMARCC2 have poor survival and prognosis, indicating KPNB1/CNBP/SMARCC2 axis as a valuable target for therapeutics of tumours." (PMID 37186134, 2023). "For instance, the knockdown of Smarcc1, Smarcd1, or Smarcd2 impaired the survival of mouse AML cells, confirming their tumor-maintaining role in this tumor type." (PMID 36810086, 2023). "Mechanistically, PRMT1 recruits the SWI/SNF chromatin remodeling complex via direct interaction with SMARCC1, leading to the transcriptional activation of insulin‐like growth factor 2 mRNA‐binding protein 2 (IGF2BP2), which enhances CBP resistance and tumor growth." (PMID 40270464, 2025). "The results showed that high expression of SMARCC1 was positively correlated with the T stage of BC but was not related to the tumor grade, tumor volume or lymph node metastasis status." (PMID 35669562, 2022). "Notably, however, deletion of either of the Smarcb1 or Smarca4 tumour suppressor subunits in MEFs markedly reduced interactions between p300 and the core SWI/SNF subunit Smarcc1." (PMID 28262751, 2017).
tumor (continued). "Analyses of ∼1000 stage I–III adenocarcinomas, by immunohistochemistry, revealed that patients with tumours displaying high levels of CBFB and SMARCC1 proteins had a significantly better overall survival rate (P=0.0001 and P=0.0275, respectively) than patients with low levels." (PMID 19156145, 2009). "Finally, proteins involved in tumor migration, invasion, malignancy and cell adhesion (Ctsd or Cathepsin D, MTCO2, Tpd52l2, Rab5c, Smarcc1) were also found to be exclusively expressed or significantly up-regulated by the AI tumorspheres compared to the AD cells." (PMID 29298329, 2018). "We did not see upregulation of reported tumour-suppressor genes, such as CDKN2A, CDKN2B and PML, and factors for neuronal differentiation, such as SMARCC1 and DLX2, in our microarray analysis." (PMID 26838672, 2016). "Patients with tumours showing strong staining had a significantly longer survival rate than patients with negative or weak scoring tumours (log-rank test; CBFB P=0.0001; SMARCC1 P=0.0275)." (PMID 19156145, 2009).
SMARCC1 also shares sentences with these, for which no sentence is quoted: experimental autoimmune encephalomyelitis (4 papers); gastric cancer (4); hepatocellular carcinoma (4); Sepsis (4); infection (3); neurologic disorders (3); adenocarcinoma (2); atopic dermatitis (2); cervical intraepithelial neoplasia (2); diabetes (2); leukemia (2); medulloblastoma (2); multiple sclerosis (2); small cell lung carcinoma (2); triple-negative breast carcinoma (2); acute myeloid leukemia (1); allergic disease (1); Alzheimer disease (1); atrial fibrillation (1); atrioventricular septal defect (1); autoimmune disease (1); bacterial diseases (1); cardiac hypertrophy (1); chronic rhinosinusitis (1); Crohn disease (1); E. coli infections (1); endometrioid carcinoma (1); epithelioid sarcoma (1); glioblastoma (1); gout (1).
A further 23 diseases each share a sentence with SMARCC1 in 1 paper.